Y_RNA (Y RNA )
Gene: Miscellaneous RNA gene on chromosome 14 (89,650,793 to 89,650,903, reverse strand). Ensembl gene ENSG00000252655.
Homologues: Orthologues: chimpanzee Y_RNA (97% identical), macaque Y_RNA (68% identical). Paralogues in human: RNY1 (84% identical), Y_RNA (81% identical), Y_RNA (80% identical), RNY1P16 (79% identical), RNY1P5 (79% identical), Y_RNA (79% identical), RNY1P2 (78% identical), Y_RNA (78% identical), Y_RNA (77% identical), RNY1P11 (77% identical), RNY1P8 (76% identical), Y_RNA (76% identical), and 90 more.